UBE2C (ubiquitin conjugating enzyme E2 C)
Diseases named in the same sentence as UBE2C in open-access papers (continued):
Sharing a sentence is not in itself a finding about the gene and the disease.
tumor (continued). "In order to avoid multicollinearity of these genes, we further performed LASSO regression analysis, and finally screened to obtain 12 genes that could be utilized to generate a scoring system for UBE2C+ tumour cells following lambda validation." (PMID 38894657, 2024). "UBE2C was identified to be the most significant DEG between tumor and normal." (PMID 37535572, 2023). "Although UBE2C is identified as a key regulator of tumor progression, the role in carcinogenesis and drug resistance of GC remains unclear." (PMID 37840753, 2023). "Its accumulation also stimulates cell proliferation, suggesting that UBE2C overexpression may play an important role in tumorigenesis and tumor progression." (PMID 37958776, 2023). "It is widely known ubiquitin-conjugating enzyme 2C (UBE2C) plays a key role in tumor progression." (PMID 36810034, 2023). "Ubiquitin Conjugating Enzyme 2C (UBE2C) is an emerging target gene for tumor progression." (PMID 37535572, 2023). "The combined pharmacological inhibition of ACLY and PLK1 may inhibit pan-tumor cell proliferation through UBE2C to achieve a “triple win”." (PMID 37958642, 2023). "In all, these results indicated that UBE2C was a pro-tumor molecule in UCEC." (PMID 37803076, 2023). "The upstream miRNAs of oncogenic UBE2C should be tumor suppressive miRNAs in HCC." (PMID 37580802, 2023). "We found that UBE2C expression is positively rated to tumor stages, LNM, and FIGO stages." (PMID 37335710, 2023). "Notably, high levels of SOX2, BMI1, and CXCR4, as well as low levels of UBE2C in the tumor core (T) significantly correlate with a greater tumor size and lymph node compromise." (PMID 38096163, 2023). "We conclude that UBE2C may hold prognostic utility in HB and that the ubiquitin pathway is a potential therapeutic target in this tumor." (PMID 37377594, 2023). "Furthermore, the tumor-suppression effect of Ube2c KO is achieved largely by accumulated DEPTOR as a substrate of UBE2C." (PMID 36548081, 2023). "Thus, our study clearly demonstrated that the UBE2C/DEPTOR axis is an oncogene-tumor suppressor cascade that regulates lung tumorigenesis triggered by KrasG12D." (PMID 36548081, 2023). "Moreover, UBE2C selectively represses autophagy, leading to enhanced cell proliferation and invasive tumor growth." (PMID 37958776, 2023). "Finally, Deptor deletion fully rescued the tumor inhibitory effect of Ube2c deletion in the KrasG12D lung tumor model, indicating a causal role of Deptor." (PMID 36548081, 2023). "In addition, we also found that UBE2C expression was correlated with tumor stage in KIRP (p < 0.001), KIRC (p < 0.001), KICH (p < 0.001), ACC (p < 0.001), TGCT (p < 0.05), LUAD (p < 0.01), LUSC (p < 0.05), and BRCA (p < 0.01)." (PMID 35804892, 2022). "It was found that UBE2C was positively correlated with the expression of tumor markers." (PMID 35568702, 2022). "UBE2C protein expression was detected prominently in the cytoplasm of invasive tumour cells." (PMID 35124721, 2022). "Gene expression database analysis followed by tumour comparison with non‐tumour tissue showed that UBE2C was upregulated in tumours and was associated with lymph node metastasis in HNSCC patients." (PMID 35615976, 2022).
tumor (continued). "It should be mentioned that although interfering with UBE2C expression inhibited tumor proliferation and induced cell apoptosis in THCA, it might pose the risk of tumor migration and invasion, thus inducing the recurrence of the disease." (PMID 35332135, 2022). "There was no reasonable explanation for these different results so far, and we speculated that UBE2C may play different roles in different pathological types of tumor cells, and may exert different effects even within the same tumor." (PMID 35332135, 2022). "Notably, the cell cycle G2/M phase gene UBE2C is specifically expressed in tumor-infiltrating cells, and the expression levels of the UBE2C gene in the tumor, adjacent tumor, and peripheral blood are basically the same." (PMID 35812372, 2022). "The high expression of UBE2C makes tumor cells resistant to masitinib." (PMID 35568702, 2022). "Multivariate analysis revealed that UBE2C expression associated with poor patients’ outcome in term of BCSS (p = 0.013, HR = 1.60, 95% CI; 1.10–2.30), independent on other prognostic parameters including LVI, tumour size, ER and HER2 status." (PMID 35124721, 2022). "Moreover, UBE2C was mainly expressed in tumor cells, which highlighted the impacts of UBE2C as a specific therapeutic strategy." (PMID 36292703, 2022). "In addition, silencing UBE2C inhibited the proliferation, colony formation, tumor spheroid growth, and sorafenib resistance induced by exogenous PRIM1." (PMID 33622397, 2021). "The expression level of UBE2C has also been related to the aggressiveness of the tumor." (PMID 34488675, 2021). "UBE2C overexpression also leads to chromosomal missegregation and tumour formation." (PMID 33541355, 2021). "Whether the tumour characteristics were significantly altered after UBE2C knockdown was then investigated." (PMID 34815392, 2021). "Indeed, UBE2C expression had already been shown to have the potentially ability to regression of tumours and was a reliable prognostic factor." (PMID 34815392, 2021). "Therefore, strict control of Ube2C activity is critical for the tight coupling of the centrosome cycle to the cell cycle as well as for tumour suppression." (PMID 34186008, 2021). "Moreover, UBE2C was significantly upregulated in a series of tumour, which were positively correlated to pathogenic condition and prognosis." (PMID 34815392, 2021). "Interestingly, it was demonstrated that UBE2C expression discriminated tumour tissue from normal epithelium and tumour-surrounding tissue with high sensitivity and specificity." (PMID 32429269, 2020). "To confirm that mTOR inhibitors can regulate the level of UBE2C, we extracted proteins from subcutaneous tumor tissues and showed that CCI779 could reduce the level of UBE2C and affect phosphorylated mTOR/AKT/PI3K." (PMID 33396624, 2020). "Moreover, overexpression of UBE2C is correlated with tumor progression, so it acts as a potential prognostic/diagnostic biomarker in various types of tumors." (PMID 32899896, 2020). "While APC itself could drive the disassembly of checkpoint complexes and the consequent inactivation of the checkpoint, high level of UBE2C observed in tumor cells was likely to promote the process 25-27." (PMID 31942195, 2020). "Moreover, it has also been reported that UBE2C overexpression correlates with tumor progression and poor prognosis in many tumors." (PMID 31067633, 2019). "The tumorigenicity of UBE2C led us to hypothesize that sustained UBE2C overexpression promotes estrogen-independent tumor growth." (PMID 32039034, 2019). "UBE2C expression is significantly higher in late-stage tumors, which might indicate its involvement in tumor progression and invasion." (PMID 31067633, 2019). "Meanwhile, we also analyzed the expression of UBE2C in PCa tumor tissues." (PMID 31646760, 2019).
tumor (continued). "Next, we re-analyzed FOXM1 and UBE2C expression data from over 7400 samples from 25 different tumor types deposited in the TCGA database and detected a positive correlation between the expressions of the two genes in all tumor types analyzed." (PMID 29596365, 2018). "As growing evidence has highlighted the importance of autophagy in anti-tumor therapies, we next investigated whether autophagy was induced and required for the attenuated UBE2C-mediated inhibition of cell proliferation." (PMID 28767320, 2017). "In addition, the expression of UBE2C was positively correlated with histological grade, tumor size, clinical stage and lymph node metastasis of BRCA." (PMID 29021715, 2017). "Furthermore, the median value of UBE2C mRNA expression levels observed in the tumor surrounding mucosa group was also significantly higher than that of the healthy esophageal tissues group." (PMID 27588470, 2016). "Additionally, we also found a slight indication that UBE2C and SCUBE2, SERPINA11, and NME5 were associated with tumor differentiation (P = 0.06 and P = 0.09, respectively), inflammatory infiltration (P = 0.09), and p16 expression (P = 0.08), respectively." (PMID 24885002, 2014). "Taken together, these data suggest that targeting of UBE2C may be a potential tool for tumor diagnosis and therapy." (PMID 23587173, 2013). "Our findings suggest that high expression of UBE2C in human NPC is closely related to tumor malignancy, and may be a potential marker for NPC progression." (PMID 23587173, 2013). "Our results were consistent with other reports describing overexpression of UBE2C in many types of tumors, and demonstrate that detection of UBE2C may be a potential biomarker for tumor diagnosis or prognostic judgment." (PMID 23587173, 2013). "Moreover, high UBE2C protein expression was positively correlated with tumor size (P=0.017), lymph node metastasis (P=0.016) and distant metastasis (P=0.015) in NPC patients." (PMID 23587173, 2013). "Abnormally high UBE2C expression was observed in various human solid cancers in the liver, thyroid, breast, colon, cervix, lung and brain, and UBE2C expression was positively correlated with invasion depth and tumor node metastasis (TNM) stage in some tumors." (PMID 23587173, 2013). "We have confirmed over-expression of MMP3, UBE2C and p16 in tumours, by IHC." (PMID 21338529, 2011). "Notably, UBE2C, a critical ubiquitination enzyme, appears to play a key role in immune evasion, potentially by inhibiting anti-tumor immune responses and reducing the immune system’s ability to recognize and eliminate tumor cells." (PMID 40290433, 2025). "Notably, our findings revealed that C2 UBE2C+ tumour cells had stronger efferent signals in the PARs signalling pathway, and actively interacted with pericytes, fibroblasts and endothelial cells, and high expression levels of the involved signalling gene PRSS3." (PMID 38894657, 2024). "Consequently, we believe that the high expression of UBE2C in LUAD patients may hinder the anti-tumor immune response, suggesting its significant role in the immune regulation of LUAD." (PMID 38370368, 2024). "Moreover, the IHC staining in the tumor tissues revealed a decreased expression of Ki-67 (cell proliferation marker) and an increased expression of cleaved-caspase 3 (apoptosis marker) in sh-UBE2C group." (PMID 38637730, 2024). "Notably, this examination singled out UBE2C as a significant DEG between tumor and normal tissues." (PMID 38577722, 2024). "Notably, UBE2C silencing also inhibited tumor growth of AML cells in nude mice." (PMID 38637730, 2024). "Similarly, a high enrichment of UBE2C in primary tumor cells was observed." (PMID 39542983, 2024). "Furthermore, Bose and colleagues demonstrated that the downregulation of UBE2C could substantially increase the sensitivity of tumor cells to radiotherapy." (PMID 38637730, 2024).
tumor (continued). "Moreover, this research further verified that the SLIT3/UBE2C axis could mediate tumor cell proliferation and migration via Wnt3A/β-catenin signaling pathway activation." (PMID 39479352, 2024). "Hence, targeting UBE2C may substantially bolster the efficacy of cisplatin treatments, reversing drug resistance and curbing tumor growth." (PMID 39033780, 2024). "UBE2C gene had significantly lower methylation level in primary tumor compared to normal tissue, which was coordinate with over-expression of UBE2C in primary tumor, indicating that hypomethylation of UBE2C might be partly responsible for the overexpression of UBE2C." (PMID 37803076, 2023). "UBE2C may play an essential role in tumour cell proliferation, migration, invasion, and metastasis." (PMID 35124721, 2022). "Moreover, high UBE2C expression might contribute to the cell adhesion process via stimulating the migration of BC tumour cells through the lymphatic vessels and starting the invasion process by activating the Wnt and PI3K signalling pathway." (PMID 35124721, 2022). "Moreover, Kaplan–Meier survival analysis showed that a higher expression of CDCA3 and UBE2C was associated with poor overall patient survival regardless of tumor stage and a higher tumor histologic grade." (PMID 34577856, 2021). "Notably, a variety of studies have revealed that UBE2C possesses a tumor stimulation function." (PMID 28767320, 2017). "In addition, we examined the expression of UBE2C-related tumor-initiation and metastasis genes." (PMID 24699941, 2014). "However, we observed that the level of UBE2C protein expression was positively correlated with tumor size (T classification) (T1–T2 vs. T3–T4, P=0.017), lymph node metastasis (N classification) (N0 vs. N1–N3) (P=0.016) and distant metastasis (M classification) (M0 vs. M1, P=0.015) in NPC patients." (PMID 23587173, 2013). "The analysis revealed that the five key genes, including BUB1, BUB1B, CDK1, UBE2C, and CCNA2, exhibited higher expression in LUAD tumor tissues compared to normal tissues in all cases." (PMID 41181148, 2025). "Tumor tissues exhibited substantial upregulation of TFF1, UBE2C, ITPKA, and IGFBP3, alongside concurrent downregulation of SELENBP1 and SLC34A2, relative to matched normal samples." (PMID 40787454, 2025). "Moreover, high UBE2C expression in stromal cells was linked to the remodeling of the tumor microenvironment, suggesting that UBE2C may promote angiogenesis and matrix remodeling by modulating the activity of fibroblasts and endothelial cells, ultimately driving tumor invasion and metastasis." (PMID 40290433, 2025). "InccRCC, a 4-gene model comprising KIF4A, UBE2C, OTX1, and PPP2R2C showed great potential to distinguish tumour tissues from normal ones." (PMID 41361459, 2025). "Additionally, when using Kaplan–Meier survival analysis, it became clear that higher levels of CDCA3 and UBE2C together were linked to poorer survival outcomes for patients, regardless of the stage of the tumor or how advanced the tumor appeared under the microscope." (PMID 38577722, 2024). "The expression levels of KIF2C, CENPA, CDC20, UBE2C, ESPL1, KIF23, and PLK1 were significantly higher in the tumor tissues of patients with a HOST-response compared to those without a HOST-response." (PMID 39201599, 2024). "UBE2C was found to be highly expressed in NPC tissues and was strongly correlated with the degree of malignancy of the tumor." (PMID 39334908, 2024). "They identified AQP5, KiSS-1, FZD7, AURKB, UBE2C, and PTTG1 as overexpressed in recurrent CNs, suggesting these genes play a role in tumor progression." (PMID 39066950, 2024). "By delving deeper into the characterization of GC cells, we identified 6 specific tumour cell subtypes: C0 PSCA+ tumour cells, C1 CLDN7+ tumour cells, C2 UBE2C+ tumour cells, C3 MUC6+ tumour cells, C4 CHGA+ tumour cells and C5 MUC2+ tumour cells." (PMID 38894657, 2024).
tumor (continued). "This underpins the functional linkage between UBE2C and CDK1, substantiated by their correlated expression in tumor tissues." (PMID 39033780, 2024). "These include the ubiquitin-conjugating enzyme E2C (UBE2C), the so-called “outer dense fibers of sperm tail 3B” (ODF3B), which is expressed in many tumor types, as well as the PDZ domain-containing protein 1 (PDZK1)." (PMID 39062119, 2024). "We extracted and re‐clustered ICC tumor cells and named those overexpressing MKI67, TOP2A, and UBE2C as proliferating tumor cells (Prolif)." (PMID 39716897, 2024). "And then, ZIC2 transcriptase-positively regulates UBE2C and activates AKT/mTOR signaling pathway to promote tumor malignant progression." (PMID 37496990, 2023). "To better understand the molecular signatures after the combined inhibition of UBE2C and PLK1 in Lv-NCI-H460 and Lv-MCF7 tumor cells, we performed an RNA-seq analysis and analyzed the DEGs." (PMID 37958642, 2023). "Here, we found that BMI1, CD44, SOX2, OCT4, UBE2C, CXCR4 CSCs marker genes are significantly upregulated, while IGF1-R, KLF4, ALDH1A1, CD133, FAM3C are downregulated in the tumor core vs healthy mucosa of 24 patients with OSCC." (PMID 38096163, 2023). "UBE2C mRNA level was significantly (p < 0.05) elevated in the UCEC samples compared with the normal tissues (normal n = 35, tumor n = 546)." (PMID 37803076, 2023). "Compared with normal tissues, IGFBP7, LBH and TFPI are low expressed in tumor tissues (P < 0.05), while KRT18, UBE2C and UBE2S were highly expressed in tumor tissues (P < 0.05)." (PMID 38077434, 2023). "In gastric cancer cells, UBE2C depletion impairs the ERK1/2 signaling pathway in vitro, while decreasing tumor volume in vivo." (PMID 37958776, 2023). "In conclusion, we constructed a five DEGs (CCNB2, CDK1, DTL, GMNN, and UBE2C)-based prognostic signature for ACC and first identified GMNN as a novel tumor biomarker for predicting the malignant progression, mitotane efficacy, and prognosis of ACC." (PMID 36539849, 2022). "P1 was enriched for cell cycle genes (e.g., TOP2A, UBE2C, CKS2), thus defined as cycling tumor cells." (PMID 35860547, 2022). "The results demonstrated that the UBE2C promoter was hypomethylated in CHOL, KIRC, and PCPG tumor tissues compared to corresponding normal tissues (p < 0.01)." (PMID 35804892, 2022). "The immunohistochemistry results demonstrated that the positive expression of Ki67, NANOG, OCT4, and SOX2 was increased in the tumor tissues of mice following ALKBH5 overexpression, the effect of which was reversed by the silencing of UBE2C." (PMID 36551544, 2022). "By analyzing the UBE2C expression in HNSCC based, we can find a significantly higher expression of UBE2C in the HNSCC compared with the tumor-side group." (PMID 36069832, 2022). "In all tumor types that had matched TCGA normal tissue data provided by the TIMER2.0 as controls, UBE2C was consistently upregulated in tumors compared to normal tissues." (PMID 35804892, 2022). "The most significant target genes were putative tumor oncogenes/promoters (TK1, KIF2C, UBE2C, AURKB) and potential tumor suppressors (CALCOCO1, CIRBP, KLHDC1, CBX7)." (PMID 36358602, 2022). "PARADIGM pathway features corresponding to the mitotic genes TPX2, RAE1, UBE2C, AURKA show increased activity in tumours with high NCS, consistent with the known role of chromosome segregation errors in W-CIN." (PMID 35326573, 2022). "Wang and his team established a model for predicting the postoperative survival of ESCC by using UBE2C and MGP genes, as well as the clinicopathological factors including the tumor staging and grade." (PMID 33859939, 2021).